MTOR (mechanistic target of rapamycin kinase)
Diseases named in the same sentence as MTOR in open-access papers (continued):
Sharing a sentence is not in itself a finding about the gene and the disease.
metabolic syndrome (continued). "The combination of tacrolimus and mTOR inhibitors was associated with increased risk of metabolic syndromes from 11.0% to 38.1%, which may contribute to the risk of CV disease and allograft dysfunction." (PMID 30473931, 2018). "The association of metabolic syndrome with HBV-related HCC raises the possibility that pre-S2 mutant-induced MTOR activation may drive the development of metabolic disorders to promote tumorigenesis in chronic HBV infection." (PMID 25909713, 2015). "Our review also suggests that mTOR inhibitors may reduce the risk of metabolic syndrome, as a positive effect was seen on all elements of the syndrome, with the exception of hyperlipidemia." (PMID 24719752, 2014). "Moreover, mTOR inhibitors are frequently associated with dyslipidemia." (PMID 36013220, 2022). "Adenosine monophosphate-activated protein kinase (AMPK) and mammalian targets of rapamycin (mTOR), as cellular nutrient and energy sensors, have been closely associated with metabolic syndrome-related diseases and might be effective targets for MetS prevention and therapy." (PMID 26371032, 2015). "Specifically, dyslipidemia is a major side effect of mTOR inhibitors and part of the insulin resistance syndrome that has emerged as a major risk factor of angiographic CAV." (PMID 38913171, 2025). "Immunosuppressive agents such as corticosteroids, calcineurin inhibitors, and mTOR inhibitors are known to contribute to post-transplant hypertension, dyslipidemia, glucose intolerance, and central adiposity." (PMID 40806925, 2025). "Although the mTOR inhibitor rapamycin exhibits notable anti-tumor activity, its clinical application is limited by metabolic side effects, particularly dyslipidemia." (PMID 40361560, 2025). "SchC effectively improves dyslipidemia through various pathways including inhibiting the PI3K/AKT/mTOR pathway, promoting autophagy, reducing pyroptosis." (PMID 40582769, 2025). "In this context, mTOR is also activated by dyslipidemia under hypoxic conditions, activating the mTOR/S6K pathway and promoting endothelial dysfunction." (PMID 39456805, 2024). "In this sense, the pathways in which mTOR acts have been postulated to be one of the molecular mechanisms linking the development of pulmonary hypertension with metabolic syndrome." (PMID 39456805, 2024). "Although the net effect of mTOR inhibition seems favorable, the use of cholesterol-lowering drugs to manage dyslipidemia remains the most recommended strategy." (PMID 38138933, 2023). "Among the target therapies, mTOR inhibitors are burdened with frequent dyslipidemia and, therefore, the etiopathology of this side effect has been the object of many studies." (PMID 35681673, 2022). "Our previous study implied that CO improved dyslipidemia and alleviated lipid accumulation by inhibiting the mTOR pathway." (PMID 35745155, 2022). "It has a positive effect, improving the treatment of psoriasis and dyslipidemia comorbidity through regulation of PI3K/Akt/mTOR and its phosphorylation pathway." (PMID 33762935, 2021). "An expanding body of literature has highlighted the contribution of probiotics and PI3K/Akt/mTOR signaling pathways in gastrointestinal disorders, metabolic syndrome, skin diseases, allergy, salmonella infection, and aging." (PMID 33615993, 2021). "By establishing an animal model of ApoE−/− mice induced by imiquimod (IMQ), we explored the effects of Liangxue Jiedu formula (LXJDF), a traditional Chinese herb medicine, on psoriasis and dyslipidemia comorbidity through PI3K/Akt/mTOR pathway." (PMID 33762935, 2021). "Mechanistically, we confirm that KD can activate AMPK/mTOR-mediated autophagy to treat metabolic syndrome in high-fat diet-fed rats." (PMID 34122092, 2021). "In conclusion, LXJDF exerts an intervention effect on psoriasis and dyslipidemia comorbidity via PI3K/Akt/mTOR and its phosphorylation pathway." (PMID 33762935, 2021).
metabolic syndrome (continued). "All components of metabolic syndrome are characterized by chronic inflammation with deregulation of the PI3K/AKT/mTOR, MAPK/EKR/JNK, Nrf2, and NF-κB signaling pathways." (PMID 32984393, 2020). "In adult studies, various side effects of mTOR inhibitors have been reported which include bone marrow suppression, dyslipidemia, immunosuppression, elevation of liver enzymes, renal dysfunction, pneumonitis and stomatitis." (PMID 29217498, 2018). "Immunohistochemistry of liver tumors in three mice models and human HCCs showed phosphorylation of mTOR to only be characteristic in TSOD mice and metabolic syndrome/NASH-associated lesions." (PMID 30469530, 2018). "The activation of mammalian target of rapamycin (mTOR) in response to inflammatory stress is involved in the progression of metabolic syndrome." (PMID 25048611, 2014). "The results showed that SchC decreased the expression levels of p-PI3K, p-Akt, and p-mTOR in the livers of chronic stress-induced dyslipidemic mice, indicating that SchC restored chronic stress-induced dyslipidemia in mice by inhibiting the PI3K/Akt/mTOR signaling pathway of autophagy injury." (PMID 40582769, 2025). "The prevalence of dyslipidemia in heart transplant recipients, observed in our study, resonates with the existing literature, highlighting the impact of maintenance therapy with mTOR inhibitors on lipid profiles." (PMID 40429597, 2025). "Moreover, since mTOR plays a crucial role in lipid metabolism, dyslipidemia has been reported to have a high prevalence among patients on mTORi." (PMID 39201363, 2024). "FoxO1 and mTOR play key roles in the onset and progression of metabolic syndrome (MetS)." (PMID 38646331, 2024). "Another common adverse metabolic side effect of systemic mTOR inhibition is dyslipidemia." (PMID 38017701, 2024). "However, the most important cause of post-transplant dyslipidemia is due to immunosuppressive drugs: CSA, TAC, and mTOR inhibitors." (PMID 36013220, 2022). "Autophagy damage by AMP-activated protein kinase (AMPK) suppression can lead to dyslipidemia in the diabetic environment, and dyslipidemia can further inhibit cardiac autophagy by enhancing mechanistic target of rapamycin kinase (mTOR) signaling of cardiomyocytes." (PMID 36091756, 2022). "Therefore, we observed the effect of LXJDF on the IMQ-induced ApoE−/− mice model to study the intervention of LXJDF on psoriasis and dyslipidemia comorbidity via regulating the PI3K/Akt/mTOR pathway." (PMID 33762935, 2021). "The present article confirmed that LXJDF could regulate the PI3K/Akt/mTOR pathway to intervene in psoriasis and dyslipidemia comorbidity by the experimental study of LXJDF on the IMQ-induced ApoE−/− mice model." (PMID 33762935, 2021). "As rapamycin (mTOR antagonist) treatment results in considerable side effects in PD patients such as dyslipidemia, antiproliferative toxicity, and renal dysfunction, acupuncture may represent as the alternative strategy to target mTOR." (PMID 34221005, 2021). "Moreover, autophagy activator RAP, inhibitor 3-MA and Atg7 siRNA were used to verify the role of AMPK/mTOR-mediated autophagy in the treatment of metabolic syndrome by KD." (PMID 34122092, 2021). "Based on an earlier RCT on proteins and insoluble fibre in participants with Metabolic Syndrome (“ProFiMet”), the role of the intestinal absorption of branched-chain-amino acids—potent activators of the mTOR pathway—was discussed In OptiFiT, faecal samples were not collected." (PMID 34254189, 2021). "mTOR hyperactivation contributes to development of the metabolic syndrome, including insulin resistance, as well as chronic inflammation, for example by promoting inflammatory cytokine secretion by cells of the innate immune system in the liver and adipose tissue." (PMID 33170123, 2020). "Obesity and metabolic syndrome are characterized by mTOR activation (Liu and Sabatini, 2020)." (PMID 33170123, 2020).
metabolic syndrome (continued). "Interestingly, p-mTOR was higher in patients with metabolic syndrome than those with different etiology, and, similar to SIRT-3, in metformin-treated than insulin-treated patients." (PMID 30917505, 2019). "It is also promising that short-term side-effects such as dyslipidemia may subside after long-term mTOR blocking therapy." (PMID 32194539, 2019). "Interestingly, we showed that in HCC patients with metabolic syndrome p-mTOR resulted more expressed than those with other etiologies." (PMID 30917505, 2019). "Considering that activation of the mTOR pathway appears characteristic of HCCs associated with metabolic syndrome unlike HCCs with HBV and HCV infection, future clinical studies should take this into account." (PMID 30469530, 2018). "In conclusion, in the present study we demonstrated that the mTOR pathway is characteristically activated in liver tumors associated with metabolic syndrome and NASH, unlike liver tumors with other etiologies." (PMID 30469530, 2018). "The management of CsA-induced nephropathy and other CsA-evoked side-effects includes therapeutic strategies devoted to minimize its use of replace by other putatively less nephrotoxic drugs, such as Sirolimus, an mTOR inhibitor, as well as to control dyslipidemia and hypertension, usually present." (PMID 24853130, 2014). "A leading study demonstrated that a high-salt diet directly induces dyslipidemia through activation of the Sterol Regulatory Element-Binding Protein (SREBP2)/Proprotein Convertase Subtilisin (PCSK9) pathway (a downstream effector of mTOR) in the liver and kidneys." (PMID 41406476, 2025). "Additionally, chronic systemic inflammation associated with metabolic syndrome and smoking may influence signaling pathways such as NF-κB, PI3K/AKT, and mTOR, which are known to affect the translation efficiency and stability of neurotrophic factors." (PMID 40722606, 2025). "As a blocker of SLC6A14, IDO1 and metabolic syndrome, α-MT can potentially have profound impact on several downstream signaling pathways such as mTOR and AhR because decreased amino acid entry into cells would impair mTOR signaling and decreased generation of kynurenine would suppress AhR signaling." (PMID 39902076, 2024). "Therefore, we speculate that AMPK/mTOR-mediated autophagy plays a key role in the treatment of metabolic syndrome by KD." (PMID 34122092, 2021). "Further studies to determine which factor is closely related to the activation of mTOR pathway and examine the association between mTOR pathway and the fibrotic process of the liver are needed to confirm the specificity of mTOR pathway activation in liver tumors with NASH and metabolic syndrome." (PMID 30469530, 2018). "For example, in individuals with metabolic syndrome (MS), it increases AMP levels by decreasing mTOR concentrations." (PMID 39290329, 2024). "The mTOR/S6K1 pathway, which promotes metabolic and cardiovascular abnormalities, is the pathway that is most affected by the effects of hypoxia and metabolic syndrome." (PMID 39456805, 2024). "↓BW, energy intake, liver oxidative stress and inflammation, hepatocyte steatosis; ↑Insulin resistance, dyslipidemia, hepatorenal function; ↓PI3K-Akt–mTOR axis, SREBP-1c/PPARγ." (PMID 37396125, 2023). "Dyslipidemia decreases “macro-autophagy/autophagy” in cardiomyocytes via inhibiting the cellular energy-sensing AMPK and stimulation of mTOR signaling." (PMID 37764807, 2023). "mTOR is a central regulator of lipid metabolism and SREBP, which already hints at mechanisms of mTOR inhibitor-induced dyslipidemia." (PMID 35159123, 2022). "To gain insight into the molecular mechanism of KD in the treatment of metabolic syndrome, we further examined the expression of AMPK/mTOR signaling pathway in liver tissues of high-fat diet-fed rats." (PMID 34122092, 2021). "Immunohistochemical analysis showed that mTOR was characteristically phosphorylated in liver tumors of TSOD mice and HCCs from metabolic syndrome cases in humans." (PMID 30469530, 2018).
metabolic syndrome (continued). "The responsiveness of mTOR pathway targets such as p706Sk to a high protein meal containing either dairy or soy foods was investigated in healthy insulin sensitive middle-aged men and those presenting with metabolic syndrome (MetS)." (PMID 25302072, 2014). "The mTOR inhibitor (mammalian target-of-rapamycin inhibitor) Everolimus (EVL) is an antiproliferative immunosuppressive drug without significant nephrotoxicity, but with side effects such as mouth ulcerations, dyslipidemia and impaired wound healing." (PMID 36832496, 2023). "Similarly, in C57BL/6 mice fed high-fat diets, GSPE reversed weight gain and dyslipidemia in mice, which was thought to be attributed to the ability of GSPE to downregulate the high-fat diet-induced increase of miR-96 and inhibition of mTOR/FOXO1 signaling." (PMID 37287997, 2023). "However, hyperglycemia and dyslipidemia can influence the autophagy process in cardiomyocytes through the AMPK and mTOR signaling pathways." (PMID 37764807, 2023). "Moreover, senescent cells were reported to contribute to metabolic syndromes regulated by AMPK, GSK3, and mTOR-signaling kinases." (PMID 34684563, 2021). "Considering these facts, adiponectin may play an important role in the activation of mTOR pathway observed in liver tumors of TSOD mice and patients with NASH and metabolic syndrome." (PMID 30469530, 2018). "The mTOR protein kinase serves as a central integrator of nutrient signaling pathways and is overactivated in cardiovascular tissues of patients with metabolic disorders such as obesity, type 2 diabetes (T2DM), and metabolic syndrome (MetS)." (PMID 28408970, 2017). "Proteome and metabolome analyses revealed the activation of mTOR in conjunction with AKT, PI3K, extracellular signal-regulated kinase 1/2 (ERK1/2) kinases, and β-catenin in the liver tumors developed in Tsumura, Suzuki, Obese Diabetic (TSOD) metabolic syndrome/T2DM NASH model mice." (PMID 37760534, 2023). "Activation of GSK3 or JNK1 was not quantified in these subjects, but previously we reported that baseline phospho‐mTOR was not increased in metabolic syndrome subjects, although post resistance training the increase in mTOR activation was nearly twice that of the control subjects." (PMID 25472611, 2014). "Finally, we discuss evidence that mTOR inhibitors may have benefits in the oncology setting and in relation to HCV-related allograft fibrosis, metabolic syndrome, and neurotoxicity." (PMID 24719752, 2014).
sarcopenia (118 papers, 2011 to 2026). Progressive decline in muscle mass due to aging which results in decreased functional capacity of muscles. "This is why mTOR and Rps6kb1 can be associated with severe sarcopenia positively and negatively, respectively." (PMID 39585121, 2024). "The association of lower activity of PI3K/AKT and potentially MTOR with the low muscle body composition type is in line with the observation that patients with cancer are at high risk of losing muscle, leading to sarcopenia or cachexia." (PMID 39769193, 2024). "mTOR is a key regulator of protein synthesis, and the inhibition of mTOR activity in muscle is closely associated with sarcopenia." (PMID 37759480, 2023). "It has been shown that the muscle-specific knockout mice of several mTOR complex coding genes develop severe myopathy, and that a decrease in mTOR pathway activity is associated to age-related sarcopenia, further highlighting the importance of these genes." (PMID 36613689, 2022). "A hyper-phosphorylated state of mTOR has been identified in sarcopenia, and calorie restriction represses this age-associated hyper-signaling in rats." (PMID 36430301, 2022). "Given the fundamental importance of mTOR signaling in the regulation of MPS, and the demonstrated contribution of down-regulated mTOR activity to aging muscle loss and sarcopenia, numerous studies have sought to define the factors underlying mTOR activation." (PMID 33672207, 2021). "Targeting and increasing mTOR expression/activity has been proposed to attenuate age-associated sarcopenia." (PMID 28115977, 2017). "In contrast, sarcopenia is consistently associated with increased toxicity to inhibitors of angiogenesis and mTOR." (PMID 28326276, 2016). "Sarcopenia is consistently associated with increased toxicity to inhibitors of angiogenesis and mTOR." (PMID 28326276, 2016). "The comprehensive results show that decorin plays a sarcoprotective role by activating the ITGB1/Akt/mTOR pathway and may serve as a potential therapeutic reagent in age‐associated sarcopenia." (PMID 41350105, 2025). "Leucine, in particular, plays a central role in activating the mammalian target of rapamycin (mTOR) pathway, which is critical for muscle protein anabolism and recovery, making it especially beneficial for athletes and aging populations at risk of sarcopenia." (PMID 40002011, 2025). "As aging is associated with sarcopenia, resistance training can stimulate muscle protein synthesis and inhibits protein degradation through the activation of the mammalian target of rapamycin (mTOR) pathway, leading to increases in muscle mass and strength." (PMID 38919474, 2024). "More specifically, under energy deficient conditions (AMP > ATP), AMPK phosphorylates mTOR, reducing mTOR signaling and, consequently, protein synthesis, a condition which leads to the development of an atrophic phenotype, including that of sarcopenia." (PMID 36079827, 2022). "Furthermore, sarcopenia is associated with alterations in the phosphoinositide PI3k/Akt/mTOR signalling pathway, which is associated with muscle protein synthesis." (PMID 35041693, 2022). "While the effect of ageing and sarcopenia on mTOR associated signaling in skeletal muscle in the fasted state has been investigated in detail its role remains unclear." (PMID 24567722, 2014). "Therefore, sarcopenia muscle of mdx mice exhibits an apparent deficiency of PI3-K/Akt/mTOR signaling." (PMID 25221510, 2014). "PI3K/Akt/mTOR signalling pathway is a potential therapeutic target for reducing fibrosis development in sarcopenia." (PMID 41350105, 2025). "The mTOR signaling pathway orchestrates fundamental biological processes, including well-documented regulatory roles in sarcopenia and skeletal muscle aging." (PMID 40941410, 2025). "In patients suffering from liver cirrhosis, it can be seen that there are alterations and changes in the mTOR signalling pathway, which is an indicator of sarcopenia." (PMID 40937507, 2025).